TET2 (tet methylcytosine dioxygenase 2)
Diseases named in the same sentence as TET2 in open-access papers (continued):
Sharing a sentence is not in itself a finding about the gene and the disease.
Parkinson disease (4 papers, 2021 to 2024). A progressive degenerative disorder of the central nervous system characterized by loss of dopamine producing neurons in the substantia nigra and the presence of Lewy bodies in the substantia nigra and locus coeruleus. "TET2 has also been suggested to play a role in microglia proinflammatory activation in Parkinson’s disease." (PMID 35386689, 2022).
renal cell carcinoma (4 papers, 2018 to 2023). "Peng Ding found that the loss of TET2 reduced the infiltration of T cells and suppressed cytokine and chemokine expression, consequently stimulating TET2 activity, and this effect can be exploited to improve immunotherapy in renal cell carcinoma." (PMID 37488178, 2023). "Although at lower frequencies than observed in hematological malignancies, TET2 alterations have also been found in various types of solid tumors, such as renal cell carcinoma, metastatic castration-resistant prostate cancer (mCRPC), lung, colon and rectal cancer." (PMID 29899831, 2018).
thymic carcinoma (4 papers, 2022 to 2025). Thymic carcinoma (TC) is a type of thymic epithelial neoplasm characterized by a high malignant potential. "TET2 loss is also associated with the development and progression of thymic carcinoma." (PMID 40116537, 2025). "Genes involved in histone modification (BAP1, 13%; SETD2, 11%; ASXL1, 4%), chromatin remodelling (SMARCA4, 4%), and DNA methylation (DNMT3A, 7%; TET2, 4%; WT1, 4%) were frequently mutated in thymic carcinomas, but not thymomas." (PMID 35884448, 2022).
thymoma (4 papers, 2022 to 2025). A neoplasm arising from the epithelial cells of the thymus. "The most frequently mutated genes within each subtype were as follows: PCLO (27%), POT1 (27%), and STAT3 (27%) in idiopathic PRCA; STAT3 (20%), DNMT3A (10%), and CUX1 (10%) in thymoma-associated PRCA; and STAT3 (54%) and TET2 (12%) in LGLL-associated PRCA." (PMID 40202536, 2025). "In a recent study, nine out of thirty nine mutated genes (23%) were involved in epigenetic regulation, with 34% of TCs exhibiting recurrent mutations in seven of them (BAP1, ASXL1, SETD2, SMARCA4, DNMT3A, TET2, and WT1), an observation which was not present for thymomas." (PMID 38338833, 2024).
thyroid cancer (4 papers, 2022 to 2025). "For example, LINC‐PINT modified miR‐767‐5p/TET2 and inhibited malignant behaviour in thyroid cancer." (PMID 34890108, 2022). "In addition, in vitro preliminary studies performed on K1 cell line treated with 5-Aza-C demethylating agent showed demethylation effects, especially upon TET2 gene, opening perspectives for thyroid cancer therapy." (PMID 41150811, 2025).
allergic rhinitis (3 papers, 2023 to 2026). Inflammation of the nasal mucous membranes caused by an IgE-mediated response to external allergens. "For instance, Tet methylcytosine dioxygenase 2 (Tet2) has also been shown to promote M2 macrophage polarization in allergic rhinitis through m5C modifications on mRNA, indicating its involvement in tissue-specific inflammatory responses." (PMID 41376856, 2026). "In allergic rhinitis mouse models, a lower abundance of 5hmC was observed in the nasal mucosa, and allergic rhinitis mice TET2 knockout developed severe allergic responses." (PMID 40599235, 2025). "In another study, we found that Ten-eleven translocation 2 (TET2) plays a very important role in the occurrence and development of allergic rhinitis." (PMID 38012545, 2023).
Arrhythmia (3 papers, 2024 to 2025). Any cardiac rhythm other than the normal sinus rhythm. "Several other studies support the role of cardiac macrophages in electrical cardiac functionality and arrhythmia development, while calcium dysregulation is considered to be worsened by inflammatory molecules (IL-1β and IL-6) in TET2-deficient macrophages." (PMID 40804878, 2025). "Eight of these associations were novel (LMNA, SMAD6, HSPB9, TMEM95, KLF1, TET2, NME3, KDM5B) and 5 genes have previously been linked to arrhythmias (SCN5A, TTN, RPL3L, PKP2, PMVK)." (PMID 38390584, 2024). "Interestingly, TET2-deficient mouse models demonstrated that inflammation via the NLRP3 inflammasome and calcium handling abnormalities in atrial cells contributed to AF susceptibility, findings that were further proved by the decreased arrhythmia incidence after NLRP3 inhibition." (PMID 40804878, 2025).
autoimmune hepatitis (3 papers, 2023 to 2025). Hepatitis caused by autoantibodies. "A recent study reported that Tet2 deficiency drives liver microbiome dysbiosis triggering liver damage and autoimmune hepatitis in mice." (PMID 40909656, 2025).
autoimmune lymphoproliferative syndrome (3 papers, 2021 to 2022). Autoimmune lymphoproliferative syndrome (ALPS) is a rare, inherited disorder characterized by non-malignant lymphoproliferation, multilineage cytopenias, and a lifelong increased risk of Hodgkin's and non-Hodgkin's lymphoma. "Bi-allelic loss-of-function variants in TET2 in humans have been associated with immunodeficiency and autoimmune lymphoproliferative syndrome (ALPS)-like phenotypes with remarkable predisposition to lymphoma." (PMID 35268351, 2022).
bone marrow failure (3 papers, 2019 to 2023). "An inherited bone marrow failure molecular panel was reported as indeterminate with two heterozygous variants detected in TET2 and SAMD9." (PMID 36810551, 2023). "Notably, the TET2 mutant clone and the PNH population are both large and stable in relative size in this patient, in contrast to TET2 mutations reported previously in patients with bone marrow failure." (PMID 31453016, 2019). "An inherited bone marrow failure panel was sent from peripheral blood and revealed a novel SAMD9 variant (heterozygous c.4460A > G; p.Lys1487Arg) and two heterozygous variants of uncertain significance, TET2 and SBDS." (PMID 37160314, 2023).
cardiac hypertrophy (3 papers, 2020 to 2025). "Mice studies with TET2-deficient bone marrow showed that TET2-mediated CHIP displayed greater features of HFpEF, with increased cardiac hypertrophy, diastolic dysfunction, and cardiac fibrosis." (PMID 39988580, 2025).
cardiomyopathy (3 papers, 2020 to 2025). A disease of the heart muscle or myocardium proper. "Adoptive transfer of unfractionated Tet2-deficient bone marrow cells in non-irradiated recipients revealed that Tet2 deficiency alters the phenotype of macrophages present in the heart and promotes cardiomyopathy in steady state conditions in aged mice without pre-existing cardiovascular injury." (PMID 33520997, 2020). "Taken together, our findings indicate that SARS-CoV-2 infection is involved in the epitranscriptomic modulation of TET2 expression in hiPSC-CMs, suggesting that TET2-driven epitranscriptomic targets play some roles in the context of SARS-CoV-2-induced cardiomyopathy." (PMID 40697650, 2025).
cerebral infarction (3 papers, 2021 to 2025). An ischemic condition of the brain, producing a persistent focal neurological deficit in the area of distribution of the cerebral arteries. "TET2 regulates changes in 5hmC in the promoter region of the Bdnf gene to affect the recovery of neurological function after cerebral ischemia injury, and loss of TET2 significantly increased the volume of cerebral infarction." (PMID 34799994, 2021). "5hmC was rapidly elevated after cerebral ischemia/reperfusion injury (CI/RI) in mice and remained elevated for 48h, TET2 expression was increased, and TET2 protein knockdown increased the area of cerebral infarction after MCAO." (PMID 40356977, 2025). "Regarding the function of TET2 in the neonatal brain, we find that knocking down TET2 worsens neonatal HI-induced brain infarct and neurological deficits and reverses the neuroprotective effect of miR-210 inhibition." (PMID 33402183, 2021). "Of importance, TET2 knockdown exacerbated brain infarct size and neurological deficits and counteracted the neuroprotective effect of miR-210 inhibition." (PMID 33402183, 2021). "We found that TET2 knockdown significantly increased brain infarct size and worsen the sensorimotor functions after neonatal HI, which is in agreement with the previous report that TET2 deficiency exacerbated infarct volume after ischemic brain injury in adult mice." (PMID 33402183, 2021). "Furthermore, we demonstrate that TET2 downregulation exaggerates HI-induced brain infarct size and neurological deficits and counteracts the neuroprotection of miR-210 inhibition in neonatal HI brain injury." (PMID 33402183, 2021).
Cerebral ischemia (3 papers, 2021 to 2025). Restriction of arterial blood supply to the brain associated with insufficient oxygenation to support the metabolic requirements of the tissue. "Another recent research also reveals that in cerebral ischemia/reperfusion, TET2 demethylated LncRNA TUG1, then subsequently promoted NLRP3 inflammasome and contributed to the inflammatory response." (PMID 36527131, 2022). "Elevated 5hmC levels may be mediated by TET3 or Tet2 in the peri-infarct region, favoring neurological recovery after cerebral ischemia." (PMID 40356977, 2025).
cholangiocarcinoma (3 papers, 2021 to 2024). A carcinoma that arises from the intrahepatic biliary tree (intrahepatic cholangiocarcinoma) or from the junction, or adjacent to the junction, of the right and left hepatic ducts (hilar cholangiocarcinoma). "Consistently, it was shown in an IDH-mutant cholangiocarcinoma model that reduced TET2 activity, via loss of α-KG, leads to reduced T cell infiltration." (PMID 39388288, 2024). "Similar mechanisms were reported in cholangiocarcinoma, mutation of IDH caused repression of TET2, which could induce immune suppression." (PMID 36203434, 2022). "Finally, the abundance of IDH1/2 mutations in gliomas and cholangiocarcinomas, but lack of TET2 mutations, are likely a reflection of TET enzymes functioning in tissue specific patterns—TET1, for example, has very recently been shown to be an oncogenic driver in IDH‐wt cholangiocarcinoma." (PMID 36618446, 2021).
chronic heart failure (3 papers, 2023 to 2025). "Specifically, patients with chronic heart failure display a pro‐inflammatory gene signature in their circulating myeloid cells, which is further aggravated in carriers of DNMT3A/TET2 CHIP‐driver mutations." (PMID 40702883, 2025). "At least for male patients with chronic heart failure, LOY ≥17% appears to be an independent risk factor for increased mortality, and its co‐occurrence with CHIP may partly confound the prognostic significance of DNMT3A/TET2 CHIP‐driver mutations." (PMID 40702883, 2025).
Cognitive impairment (3 papers, 2018 to 2021). Abnormal cognition is characterized by deficits in thinking, reasoning, or remembering. "Reduced TET2 expression has also been implicated in altered neurogenesis and cognitive impairment." (PMID 34639019, 2021). "Future research could assess changes in these enzymes at older stages to see if SAMR1 mice fail to maintain high Tet2 levels as age-related cognitive impairment progresses." (PMID 30619445, 2018). "Therapeutic approaches by inhibiting methylation using 5-iodotubercidin, increasing 5 hmC and TET2 through force running to alleviate hippocampal cognitive deficits induced by radiation further confirm the important roles epigenetics may play in radiation-induced cognitive impairment." (PMID 33327654, 2020).
diabetic retinopathy (3 papers, 2017 to 2024). "Studies have shown that tet methylcytosine dioxygenase 2 (TET2) is highly expressed in diabetic retinopathy (DR), which reduces the DNA methylation of downstream gene promoters and activates the transcription." (PMID 38172938, 2024).
frontotemporal dementia (3 papers, 2021 to 2024). Frontotemporal dementia (FTD) comprises a group of neurodegenerative disorders, characterized by progressive changes in behavior, executive dysfunction and language impairment, as a result of degeneration of the medial prefrontal and frontoinsular cortices. "Rare variations of TET2 were often found in patients with early onset Alzheimer’s diseases (AD) and frontotemporal dementia (FTD)." (PMID 39149518, 2024). "A recent study showed that rare LoF or non-coding TET2 variants were significantly enriched in populations with early-onset Alzheimer’s disease (EOAD) and frontotemporal dementia (FTD)." (PMID 36814905, 2023).
hepatoblastoma (3 papers, 2019 to 2024). Hepatoblastoma (HB) is a malignant hepatic tumor and is the most common pediatric liver cancer. "During hepatoblastoma, a general disruption in the expression of genes from the epigenetic machinery was observed, mainly upregulation of UHRF1, TET1, and TET2, in association with an enrichment of 5 hmC content." (PMID 39684755, 2024). "In the context of hepatoblastoma, the enrichment of 5-hydroxymethylcytosine has been associated with disrupted expression of UHRF1, TET1, and TET2." (PMID 39595571, 2024). "We observed in hepatoblastomas a general disrupted expression of these genes from the epigenetic machinery, mainly UHRF1, TET1, and TET2 upregulation, in association with an enrichment of 5hmC content." (PMID 31249594, 2019).
HIV-1 infection (3 papers, 2019 to 2024). The type species of lentivirus and the etiologic agent of acquired immunodeficiency syndrome (AIDS). "In the context of HIV-1 infection, TET2 protein degradation via Vpr protein similarly sustains IL-6 production, which enhances virus replication." (PMID 35115654, 2022). "In macrophages, Vpr-induced TET2 depletion prevents efficient resolution of IL-6 induction during HIV-1 infection, which enhances HIV-1 infection in macrophages." (PMID 31431548, 2019). "We have recently discovered that Vpr targets the DNA demethylase TET2 for degradation, which leads to sustained IL-6 expression and elevated second-round HIV-1 infection." (PMID 31431548, 2019). "The Vpr-TET2 axis enhances HIV-1 infection in MDMs by reducing IFITM3 expression via a TET2 dioxygenase-dependent mechanism and by sustaining IL-6 induction via TET2 dioxygenase-independent mechanisms." (PMID 31431548, 2019). "It is likely that Vpr still possesses TET2-indepedent activity that can further enhance HIV-1 infection in macrophages, as suggested by the partial Vpr activity to enhance HIV replication in TET2-depleted cells." (PMID 31431548, 2019). "The Vpr-TET2 axis may provide a novel target to develop anti-HIV drugs to inhibit HIV-1 infection and pathogenesis." (PMID 31431548, 2019). "The Vpr-TET2 axis may provide a novel target to develop therapeutics to inhibit HIV-1 infection and pathogenesis." (PMID 31431548, 2019). "The Vpr-TET2 axis may serve as a novel target to develop anti-HIV drugs to inhibit HIV-1 infection and pathogenesis." (PMID 31431548, 2019). "We further analyzed spreading HIV-1 infection of Vpr+ and Vpr− HIV-1 in MDMs for 6 days with depletion of TET2 or IFITM3 treated with IL-6 neutralizing antibody." (PMID 31431548, 2019). "The Vpr-TET2 axis enhances HIV-1 replication in MDMs by reducing IFITM3 expression and by sustaining IL-6 induction after HIV-1 infection." (PMID 31431548, 2019). "During HIV-1 infection of macrophages, in the absence of Vpr, TET2 demethylates the IFITM3 promoter, relieving suppression, contributing to the antiviral response." (PMID 38951492, 2024).
mast cell disease (3 papers, 2012 to 2019). "In the current study, we investigate the biological relevance of loss of TET2 in the context of KIT D816V associated mast-cell disease both in vivo in a mouse model and in vitro in human cells." (PMID 24788138, 2014). "We successfully sorted mast cells and monocytes from a new patient with ISM and urticaria pigmentosa, and a TET2 mutation (Q962X) was identified in peripheral blood MNCs, sorted monocytes and sorted mast cells, but not in CD3+ cells (data not shown)." (PMID 22905207, 2012).
nasopharyngeal carcinoma (3 papers, 2020 to 2024). A carcinoma arising from the nasopharyngeal epithelium. "Combined with previous study, we speculated TET2 interacts with the PKM2 isoform in nasopharyngeal carcinoma and inhibits PKM2-mediated glycolysis." (PMID 32774157, 2020). "Our group demonstrates TET2 delays nasopharyngeal carcinoma progression by interacting with PKM and suppressing glycolysis, suggesting that TET2 may serve as a new therapeutic target for NPC." (PMID 32774157, 2020). "While PKM1 isoform differs from PKM2 on 389-433 amino acids sequence, whether TET2 interacts with PKM1 and the relative expression ratio of PKM1 and PKM2 in different nasopharyngeal carcinoma cell lines need to be clarified in future." (PMID 32774157, 2020).
neuroblastoma (3 papers, 2016 to 2025). Neuroblastoma (NB) is the most common solid, extracranial childhood tumor. "To demonstrate this and to validate that this Tet2 targeting gRNA indeed was capable of efficiently editing its intended target site, we transfected the mouse neuroblastoma cell line Neuro-2A (N2A), with the Cas9/gRNA expression plasmid pX330, that contained the Tet2 gRNA (pX330Tet2)." (PMID 27587996, 2016). "E3 altered the interaction of SUZ12, LSD1, and DNMT1 with ERα in endometrial cells and altered the interaction of TET2 and DNMT1 with ERα and ERβ in neuroblastoma cells." (PMID 35491423, 2022).
parathyroid carcinoma (3 papers, 2018 to 2023). "Barazeghi et all (2016) and previous studies from the literature also underlined the implication of TET2 (ten-eleven translocation) gene expression in the pathogenesis of parathyroid cancer." (PMID 36984449, 2023). "Recently, we have shown that in parathyroid carcinomas undetectable/low levels of 5hmC is associated with aberrant expression of TET1 and TET2 and that both genes have cell growth regulatory roles in parathyroid tumor cells." (PMID 30045709, 2018).
prostate adenocarcinoma (3 papers, 2023 to 2025). "Note that the potential tumor-suppressive effect of TET2 in prostate adenocarcinoma is likely to be linked with enhanced immune cell infiltration." (PMID 37325635, 2023). "TET2 expression was measured in patients with various types of cancers, and it was upregulated in low-grade glioma patients but downregulated in ccRCC, ovarian cancer and prostate adenocarcinoma patients." (PMID 37325635, 2023).